COL11A1 (collagen type XI alpha 1 chain)
Diseases named in the same sentence as COL11A1 in open-access papers (continued):
Sharing a sentence is not in itself a finding about the gene and the disease.
cancer (continued). "Its alpha 1 chain (COL11A1) has been found to be upregulated in a variety of cancers and is supposed to promote proliferation, angiogenesis, invasion and drug resistance of cancer cells." (PMID 35008401, 2022). "Other transcription factors known to regulate COL11A1 expression in the context of cancer include SP1, B-myb, and c/EBPβ." (PMID 35847935, 2022). "In this review, we provide a comprehensive overview of the biological functions of COL11A1 in cancer and discuss how COL11A1 mediates the crosstalk between cancer cells and the tumor microenvironment (TME) to regulate the phenotypes of cancer cell and CAF." (PMID 35847935, 2022). "Gene expression arrays of 38 human tumors were downloaded from TCGA database, and the difference of COL11A1 expression between cancer tissues and corresponding adjacent tissues was analyzed by R language package DESeq2 and TIMER database." (PMID 36160004, 2022). "In these cancers, the expression of COL11A1 positively correlates with tumor progression and lymph node metastasis." (PMID 35847935, 2022). "COL11A1 is one of the top genes in the gene signature that predicts an outcome to standard chemotherapy in ovarian and other cancers." (PMID 35847935, 2022). "Multiple studies have proven that COL11A1 participates in cancer progression through various signaling pathways." (PMID 35847935, 2022). "COL11A1 promotes cell proliferation and inhibits cell apoptosis by activating Akt in cancer cells and was demonstrated to be involved in chemoresistance." (PMID 36293285, 2022). "We focused on EMT and cell stemness programs to better understand the intricate molecular mechanisms by which COL11A1 regulates cancer development." (PMID 35327583, 2022). "This ability of COL11A1 to alter the metabolic adaptation of cancer cells benefits the cells to survive the harsh environments generated by chemotherapy." (PMID 35847935, 2022). "But the expression and biological function of COL11A1 in cancers are still controversial and tumor-specific." (PMID 36389832, 2022). "GEPIA database also revealed that COL11A1 was significantly correlated with cancer stage in BLCA, ESCA, HNSC, LUAD and STAD." (PMID 35892083, 2022). "Although there is no current therapy specifically designed to target COL11A1 in cancer, there are certain drugs that target COL11A1 signal, some of which have been or are currently being tested in clinical trials." (PMID 35847935, 2022). "Screening by MutSig2CV across 27 cancers identified COL11A1, COL13A1, COL19A1, COL1A2, and COL4A4 as borderline significantly mutated, and 2 collagens were significant in the TCGA stomach adenocarcinoma (STAD)." (PMID 35120467, 2022). "COL11A1 overexpression has only been observed in desmoplastic areas of the tumors, which are composed primarily of CAFs in cancers." (PMID 35847935, 2022). "As COL11A1 tends to accumulate in tumor tissues and promote malignant progression of human cancer, with lower expression levels in normal tissues, targeting COL11A1 has become an attractive strategy for the treatment of various cancers." (PMID 35847935, 2022). "LAMA1, CHAD, ITGA8, and COL11A1 consistently showed hypermethylation in more than half of cancer types; on the contrary, TNN, SPP1, COL6A6, and TNR consistently showed hypomethylation in more than half of types of cancer." (PMID 36311789, 2022). "COL11A1 is upregulated in chemoresistant carcinomas including OC and has subsequently been suspected to be functionally involved in the process." (PMID 34378164, 2022). "Although follow up data was not available, these results are in line with previous studies reporting a correlation between bulk COL11A1 expression and an adverse outcome for many carcinomas." (PMID 34378164, 2022). "High COL11A1 expression level is frequently correlated with tumor invasion, recurrence and poor survival in various carcinomas." (PMID 36232952, 2022).
cancer (continued). "In summary, these studies suggest that COL11A1 activates survival signaling in cancer cells, with most studies agreeing that COL11A1 activates Akt to promote cell survival." (PMID 33668097, 2021). "There is also a positive correlation between the stage of cancer and COL11A1 expression, COL11A1 expression and matrix stiffness, disease progression and increased ECM." (PMID 33668097, 2021). "COL11A1, a collagen subtype critical for collagen fiber assembly, is upregulated in various types of cancer." (PMID 34183642, 2021). "Representative tumor sections showed higher ITGA11 and COL11A1 expressions in intratumoral cancer epithelium and cancer stroma compared to normal lung tissue." (PMID 33682233, 2021). "Intratumoral expression levels (H‐score) of ITGA11 and COL11A1 in cancer epithelium and cancer stroma were significantly higher than those in normal lung tissue." (PMID 33682233, 2021). "It should be noted that majority of these mechanistic studies were performed in COL11A1-overexpressing cancer cells which only contribute to a minor part of COL11A1 signal in the tumor setting." (PMID 33668097, 2021). "FAO, a metabolic pathway upregulated by COL11A1, has been shown to be a driver of cancer stemness as well." (PMID 33668097, 2021). "This ability of COL11A1 to alter the metabolic adaptation of cancer cells benefits the cancer cells to survive the harsh environments generated by chemotherapy." (PMID 33668097, 2021). "We will also discuss how COL11A1 can serve as a promising biomarker and therapeutic target to treat cancer as well as the remaining challenges to address our knowledge gaps in COL11A1 biology." (PMID 33668097, 2021). "COL11A1 overexpression has been observed in many cancer types and has also been shown to stimulate pro-survival signaling across different cancer types as well." (PMID 33668097, 2021). "We further examined the expression and localization of ITGA11 and COL11A1 in human CAFs and tumor tissues derived from NSCLC patients to validate ITGA11 and COL11A1 as specific cancer stroma biomarker." (PMID 33682233, 2021). "There is evidence that cancer cells that are resistant to the commonly used cancer therapeutic drugs, express high levels of COL11A1." (PMID 33668097, 2021). "COL11A1 also promotes cancer cell migration, metastasis, and therapy resistance by activating pro-survival pathways and modulating tumor metabolic phenotype." (PMID 33668097, 2021). "COL11A1 expression in CAFs is associated with co-expression of a panel of EMT- and stemness-regulating genes across 13 different cancer types." (PMID 33668097, 2021). "Another transcription factor that is also known to regulate COL11A1 expression in a cancer context is B-myb." (PMID 33668097, 2021). "We assessed the mechanisms related to the functions of COL11A1/Akt signaling in regulating cancer cell apoptosis." (PMID 33531986, 2021). "Although not explored in this study, it is an intriguing possibility that COL11A1-expressing bone marrow-derived mesenchymal cells differentiate into COL11A1-expressing tumor endothelial cells upon contact with cancer cells." (PMID 33668097, 2021). "Although COL11A1 expression in normal tissues is very low, COL11A1 expression is significantly upregulated in many types of cancer." (PMID 33668097, 2021). "Despite our increased understanding of COL11A1 functions in chemoresistance, the roles of COL11A1 in cancer stemness, tumor dormancy, inflammation and recurrence are still unclear." (PMID 33668097, 2021). "We demonstrated that COL11A1 phosphorylated AktSer473, promoting proliferation of cancer cells and inhibiting their apoptosis." (PMID 33531986, 2021). "In ovarian, gastric, esophageal, pancreatic, lung, and HNSCC cell lines si/shRNA-mediated knockdown of COL11A1 significantly abrogates the invasive potential of cancer cells." (PMID 33668097, 2021). "Other studies have shown that high expression of COL11A1 is related to poor clinical prognosis in diverse cancers." (PMID 34938313, 2021).
cancer (continued). "TGF-β, a growth factor known to induce COL11A1 expression, inhibition has been explored as an anti-cancer therapy in the clinic." (PMID 33668097, 2021). "Multiple studies that analyzed human pan-cancer matrisome demonstrate that COL11A1 is one of the top genes upregulated in late stage aggressive cancers." (PMID 33668097, 2021). "Through binding to specific receptors and activating several key cell-survival signaling pathways, COL11A1 can promote cancer progression, metastasis and drug resistance." (PMID 33668097, 2021). "Several inhibitors that are currently being tested in clinical trials for cancer or used in clinic for other diseases, can be potentially used to target COL11A1 signaling." (PMID 33668097, 2021). "The pan-cancer consensus ranking of protein-coding genes in terms of LINC01614 corresponds precisely to the COL11A1-expressing CAF signature." (PMID 34283835, 2021). "It should be noted that most of COL11A1 signaling molecules are also critical regulators of cancer stemness phenotype (e.g., TGFβ, TWIST, c/EBPb, DDR2, Akt, Scr)." (PMID 33668097, 2021). "Although there is no current therapy specifically designed to target COL11A1 in a cancer context, there are certain drugs that target either upstream or downstream molecules of COL11A1, some of which have been or are currently being tested in clinical trials." (PMID 33668097, 2021). "COL11A1 is one of the top genes in the gene signature that predicts outcome to standard chemotherapy in ovarian and other cancers." (PMID 33668097, 2021). "Further study of COL11A1 will facilitate the design of personalized targeted therapies to improve clinical outcome in many cancer types." (PMID 33668097, 2021). "Further supporting a possible role for COL11A1 in cancer are observational data linking it to angiogenesis, drug resistance and metastasis." (PMID 34584216, 2021). "Some miRNA and long non-coding RNA (lncRNA) were involved in the regulation of COL11A1 in cancer cells." (PMID 34944877, 2021). "Collectively, this review underscores the role of COL11A1 as a promising biomarker and a key player in cancer." (PMID 33668097, 2021). "It tends to increase the expression of COL11A1 at advanced stages of cancer (Stage 3 > Stage 2 > Stage 1) and decrease along with the increase in the age group of patients." (PMID 33597969, 2021). "It is interesting to note that the expression of COL11A1 is elevated post chemotherapy in several cancer types and can mediate resistance to cisplatin chemotherapy." (PMID 33668097, 2021). "The influence of COL11A1 and its associated gene triggers alteration of APC for around 66.7% that resulted in the overactivation of Wnt signaling pathways leading to cancer development." (PMID 33597969, 2021). "We confirmed COL11A1 mutations by Sanger sequencing and detected COL11A1 protein in every cSCC from an independent series (n = 76) of human tumors, verifying its presence in this cancer." (PMID 34584216, 2021). "The authors performed extensive computational analyses of single-cell RNAseq data across many cancer types, to identify that naturally occurring normal human adipose-derived stromal cells transform into COL11A1-expressing CAFs." (PMID 33668097, 2021). "High collagen type XI alpha 1 (COL11A1) levels are associated with tumor progression, chemoresistance, and poor patient survival in several cancer types." (PMID 34944877, 2021). "They show that among several factors that drive malignancy, COL11A1 is the only collagen gene upregulated in the matrisome of aggressive cancer." (PMID 33668097, 2021). "RT-qPCR demonstrated that COL11A1 was highly expressed in cancer tissues compared to adjacent normal tissues (p < 0.05)." (PMID 31938021, 2020). "Our previous report indicated that COL11A1 enhances cell sensitivity to anti-cancer drugs via the activation of the Akt/c/EBPβ pathway in concert with attenuated PDK1 ubiquitination and degradation." (PMID 32194423, 2020).
cancer (continued). "Meanwhile, a prior research reported that COL11A1 was highly expressed in cancers and potentiated the invasion by coordinating with invasion-sensing biomarkers." (PMID 31938021, 2020). "The c/EBPβ-binding site on the COL11A1 promoter (−541/−203) region has been identified as the major determinant of anti-cancer drug-induced COL11A1 expression." (PMID 30975980, 2019). "COL11A1 mRNA is significantly increased in various types of cancers, and its overexpression in CAS is associated with poor prognosis in human mCA." (PMID 31308057, 2019). "Top five up-regulated genes in malignant tumours were COL11A1, SFRP2, LCN2, COL2A1 and H19, while top up-regulated genes in benign tumours were MMP3, MMP1, AREG, PTHLH and SFRP2." (PMID 30517191, 2018). "Among malignant tumours, maximum fold change was observed for COL11A1 gene (Log2 FC = 4.8), while among benign tumours maximum fold change was observed with MMP3 gene (Log2 FC = 6.6)." (PMID 30517191, 2018). "ECM-receptor interaction and focal adhesion pathways were closely related to tumor invasion and metastasis, in which three proteins of ITGA2, COL1A1 and COL11A1 were also behaved up-regulation trend in cancer, except FLNC." (PMID 27626164, 2016). "Two genes, actin-organizing protein KLHL1 at 13q21.33 and COL11A1 (collagen, type XI, alpha 1) at 1p21.1 were detected as joint deletions in all four cancer types (breast, ovarian, endometrial, and cervical, BOEC)." (PMID 27876019, 2016). "Described gene set was co-expressed with COL11A1 and was reportedly observed in different types of cancer (ovarian, colon, breast, pancreatic, and gastric)." (PMID 27028324, 2016). "Ten out 11 cases relapsed as carcinoma presents positive staining for COL11A1, while just 17 out of 51 cases with benign behaviour present immunostaining." (PMID 26448946, 2015). "Previous observations on the expression of COL11A1 in other cancers were limited to differential gene expression analyses validated by quantitative RT-PCR, Northern blots and/or in situ mRNA hybridization." (PMID 24194920, 2013). "A computational analysis of gene expression in multiple cancers reveals that overexpression of COL11A1 and other genes is a high-specificity biomarker for cancer invasion and predicts the response to neoadjuvant therapy." (PMID 24194920, 2013). "Finally, we realized that COL11A1 has been identified as a potential metastasis-associated gene in other types of cancer as well, such as in lung, and oral cavity, suggesting that the MAF signature may be present in a subset of high stage samples of most if not all epithelial cancers." (PMID 21047417, 2010). "The precise contribution of COL11A1 to tumor progression and metastasis remains undefined and could vary significantly depending on the cancer's stage of development." (PMID 39845732, 2025). "The precise structural organization of COL11A1 in cancer is not yet fully understood." (PMID 41462920, 2025). "It has been observed that COL11A1 is overexpressed in the desmoplastic stroma of tumors predominantly formed by cancer-associated fibroblasts and is not expressed by fibroblasts associated with inflammatory diseases." (PMID 41462920, 2025). "In contrast to classical markers, COL11A1 is predominantly expressed in stromal cells particularly in cancer-associated fibroblasts (CAFs), rather than in tumor epithelial cells." (PMID 41462920, 2025). "Data support the physiological importance of COL11A1 specifically in cancer." (PMID 38525245, 2024). "We also found that COL11A1 is overexpressed in many cancer types." (PMID 38649961, 2024). "The correlation between COL11A1 and immune checkpoint genes in human cancers was also evaluated." (PMID 38649961, 2024). "All the evidence suggests the importance of COL11A1 in cancer progression." (PMID 38806505, 2024).
cancer (continued). "Notably, COL11A1 expression is frequently upregulated in various cancers, with elevated levels correlating with adverse clinical outcomes, including poor survival, chemoresistance, and recurrence in numerous solid cancers." (PMID 38392197, 2024). "COL11A1 has been linked with ECM remodeling and invasiveness in some cancers." (PMID 38277211, 2024). "Moreover, previous studies have implicated ACKR3, CHAF1B, CHEK1, and COL11A1 as being involved in cancer cell proliferation, while CA9, CHAF1B, and COL11A1 play roles in cancer invasion and migration." (PMID 38652547, 2024). "According to these results, we speculate that COL11A1+ FBs are CSFs that specifically exist across different cancer types." (PMID 36744260, 2023). "Based on these findings that COL11A1 could promote tumor progression, COL11A1 has been considered as a potential therapeutic target for cancer treatment." (PMID 36744260, 2023). "The same group also found that COL11A1 could be used as a specific marker for activated CAFs, and COL11A1 expression was correlated with tumor stage, tumor grade and patients’ outcome in 13 types of carcinomas." (PMID 36744260, 2023). "Importantly, emerging evidence suggests that COL11A1 is a cancer progression-correlated gene that can facilitate tumor growth, migration, invasion, metastasis, and chemotherapy resistance." (PMID 35892083, 2022). "COL11A1 overexpression has been shown to upregulate chemoresistance, and the roles of COL11A1 in cancer stemness, tumor dormancy, inflammation, and recurrence remain unclear." (PMID 35847935, 2022). "COL11A1 expression in 24 cancer types was evaluated using the TCGA database." (PMID 35892083, 2022). "Furthermore, COL11A1 negatively correlated with B cells, CD4 and CD8 cells, but positively associated with cancer-associated fibroblasts." (PMID 36389832, 2022). "However, several studies have found that cancer cells secrete the COL11A1 they produce into the ECM, to regulate their own biological behavior as well as that of the surrounding cancer cells." (PMID 35847935, 2022). "Moreover, previous studies revealed that COL11A1 strengthens cancer cell invasion through cooperating with invasion-sensing biomarkers." (PMID 35669376, 2022). "Recently, COL11A1 has been recruited as novel biomarker and a key player in cancer." (PMID 35736209, 2022). "GEPIA database was utilized to validate COL11A1 expression in 14 cancer types." (PMID 35892083, 2022). "Collagen type XI alpha 1 (COL11A1) as an oncogene has been reported in several malignant tumors." (PMID 35892083, 2022). "Our findings elucidate the mode of COL11A1 expression in very different carcinoma types and may aid to categorise tumours in the setting of possible future COL11A1-related therapies." (PMID 34378164, 2022). "Understanding which cancers may likely benefit from HSP27 inhibition therapy by proxy of the relevant biomarkers (such as COL11A1, SPARC, and potentially type I collagen) may lead to more treatment successes." (PMID 34638339, 2021). "Targeting COL11A1 receptors could be another attempt to inhibit COL11A1’s pro-survival signaling that confers chemoresistance to cancer cells." (PMID 33668097, 2021). "More promising FAO inhibitors including perhexiline, ranolazine, and trimetazidine, which are currently being used to treat angina pectoris, could potentially be repurposed to treat COL11A1-high cancers." (PMID 33668097, 2021). "Therefore, COL11A1/integrinα1β1/DDR2 signaling to inhibit the apoptotic process through PI3K/Akt has been demonstrated in other cancer types 33-35." (PMID 33531986, 2021). "COL11A1 encodes the collagen type XI α1 chain, a minor fibrillar collagen, which is a part of the common gene signatures associated with poor clinical outcomes and is known as a surrogate CAF biomarker in diverse cancer stroma." (PMID 33682233, 2021). "Overexpression of COL11A1 could accelerate cancer cell proliferation, invasion, migration, and metastasis, and resist chemotherapy sensitivity." (PMID 34938313, 2021).